LIMASI (lncRNA inflammatory and mucous response associated, antisense to ICAM1)
Synonyms: LASI; AC011511.2
Gene: Long non-coding RNA gene on chromosome 19 (10,239,048 to 10,290,813, reverse strand). Ensembl gene ENSG00000266978.
Diseases named in the same sentence as LIMASI in open-access papers:
LIMASI is named in the same sentence as 11 diseases in open-access papers, as found by Europe PMC text mining. Sharing a sentence is not in itself a finding about the gene and the disease.
LIMASI shares sentences with these, for which no sentence is quoted: infection (7 papers); cystic fibrosis (3); abscess (1); allergic asthma (1); bacterial infections (1); chronic lung infection (1); co-infection (1); healthcare-associated infections (1); Pleural effusion (1); staphylococcal infection (1); tumor (1).